OR51E2 (olfactory receptor family 51 subfamily E member 2)
Diseases named in the same sentence as OR51E2 in open-access papers (continued):
Sharing a sentence is not in itself a finding about the gene and the disease.
breast carcinoma (3 papers, 2021 to 2024). "OR51E2 overexpression has been linked to cancer cell proliferation and migration, while OR2B6 overexpression in breast carcinoma contributes to invasive behavior and metastatic potential." (PMID 39769144, 2024). "Several studies have demonstrated their potential as therapeutic targets and prognostic biomarkers in cancer, with OR51E2, also known as the prostate-specific G-protein-coupled receptor, and OR2B6 showing overexpression in prostate and breast carcinomas, respectively." (PMID 39769144, 2024).
prostate intraepithelial neoplasia (3 papers, 2012 to 2018). A neoplastic proliferation of the epithelial cells that line the acini and the ducts of the prostate gland. "OR51E2 is present in healthy prostate tissue and shows significantly increased expression in prostate intraepithelial neoplasia (PIN), prostate adenocarcinoma (PC), and castration-resistant prostate cancer (CRPC)." (PMID 29892571, 2018).
asthma (2 papers, 2016 to 2018). "OR51E2 has been shown to modulate proliferation and cytoskeletal remodeling in ASM from both asthmatics and non-asthmatics, implying that modulation of OR51E2 signaling may be beneficial in asthma." (PMID 30542293, 2018).
colitis (1 paper, 2024). Inflammation of the colon. "The transcription of OR51E2 is significantly reduced in mouse models with DSS-induced colitis." (PMID 38721154, 2024).
Hypertension (1 paper, 2022). The presence of chronic increased pressure in the systemic arterial system. "Butyric acid diminishes angiotensin II-induced hypertension in mice, and some SCFAs are known to have ligands that can potentially be engineered as therapeutic targets for hypertension (e.g., GPR41, GPR43, GPR109a in mice and SCFA receptors such as Olf78/OR51E2 in human)." (PMID 36145077, 2022).
medullary thyroid cancer (1 paper, 2023). "Therefore, OR51E2 may be a novel diagnostic and therapeutic target for medullary thyroid cancer." (PMID 37371783, 2023). "Specifically, we found that OR51E2 and OR51E1 were expressed in thyroid cancer cell lines and human medullary thyroid cancer cells." (PMID 37371783, 2023).
proliferative vitreoretinopathy (1 paper, 2017). Vitreoretinal membrane shrinkage or contraction secondary to the proliferation of primarily retinal pigment epithelial cells and glial cells, particularly fibrous astrocytes, followed by membrane formation. "Therefore, we conclude that OR51E2 represents a promising therapeutic target protein for the treatment of proliferative RPE disorders, such as proliferative vitreoretinopathy." (PMID 29249973, 2017).
tumor (23 papers, 2012 to 2025). "Silencing of OR51E2 favored polarization of tumor-conditioned macrophages toward a proinflammatory phenotype, while hindering acquisition of a protumoral status." (PMID 40588561, 2025). "PSGR/OR51E2 expression levels have been found to correlate with prognosis, and a mouse model of PSGR/OR51E2 overexpression suggests that this receptor does indeed play a role in tumor development." (PMID 30542293, 2018). "The activation of OR51E2 leads to inhibition of cancer cell proliferation making it a novel tumor target for therapy." (PMID 28273117, 2017). "In agreement with previous studies, OR51E2 gene (olfactory receptor, family 51, subfamily E, member 2) exhibited differential expression levels in normal and tumor tissue samples (FC = 8.54, P < 0.001, FDR < 000.1)." (PMID 28910345, 2017). "Our results thus support the role of OR51E2 in the β-ionone observed effects, and suggest that gallein could be a potential new agent in personalized medicine of the tumours expressing OR51E2." (PMID 29084601, 2017). "Since NE-like tumor cells express AMACR, we investigated whether activation of OR51E2 also increased AMACR levels." (PMID 29892571, 2018). "Similarly, PSGR/OR51E2 has been tied to cancer cell invasiveness and is a tumor antigen recognized by CD8+ T cells." (PMID 30542293, 2018).
cancer (20 papers, 2011 to 2025). A tumor composed of atypical neoplastic, often pleomorphic cells that invade other tissues. "In our study, we selected six human olfactory receptors including OR51E2, OR52cs, TAAR9, OR51E1, OR1A1, and OR1A2 that have been linked with research for the possible development of cancer treatment and detection methods." (PMID 39944883, 2025). "Despite this, our data showed that individuals with PSA level ≤ 4.0 ng/mL can be distinguished into cancer-free or PCa-affected based on the expression levels of OR51E2 and SIM2 genes." (PMID 28910345, 2017). "Until now, only one OR gene, prostate-specific G-protein-coupled receptor (PSGR/OR51E2), has been connected to cancer." (PMID 21542898, 2011). "Thus, OR51E2 represents an interesting therapeutic target for the development of novel therapies to treat cancer or pigmentation disorders." (PMID 29249973, 2017). "Thus, the utility of modulating OR51E2/PSGR in cancer is currently unclear." (PMID 30542293, 2018). "Although classically associated with olfactory functions, OR51E2 is also expressed in non-olfactory tissues such as the intestine and adipose tissue, where it has been implicated in diverse physiological processes, including fat metabolism, cell differentiation, and cancer biology." (PMID 41227413, 2025). "Two studies have reported promising results for cancer detection using PSGR (prostate-specific G-protein coupled receptor, official gene name OR51E2, olfactory receptor 51E2)." (PMID 32630458, 2020). "One of these cancer-related receptors is OR51E2, known as well as the prostate-specific G protein-coupled receptor (PSGR) as this GPCR was first detected in the prostate before it was classified as an olfactory receptor by sequence homology." (PMID 29167480, 2017). "OR51E2 is also known as a prostate-specific G-protein coupled receptor (PSGR), and its in vitro inhibition retarded cell growth, suggests its potential as a target for cancer therapy." (PMID 28910345, 2017). "It is important to mention that OR2B6 unlike OR51E1 and OR51E2 lacks expression in healthy tissues, ensuring that the high expression does not come from an increase of a specific cell type but from the existence of the different transcript repertoire in cancer cells." (PMID 29497600, 2018).
adenocarcinoma (1 paper, 2013). A common cancer characterized by the presence of malignant glandular cells. "Multiple genes involved in olfactory transduction and neuroactive ligand-receptor interaction including OR13J1, OR51E2, GNAL, and GRIK1 were also found by this study to be mutated in the adenocarcinoma, suggesting these two classes of genes warrant further investigation." (PMID 23301059, 2013).
OR51E2 also shares sentences with these, for which no sentence is quoted: benign prostatic hyperplasia (1 paper); bone metastasis (1); colorectal adenoma (1); lung carcinoma (1); lymphoid cancers (1); thyroid cancer (1).